RUNX1 (RUNX family transcription factor 1)
Diseases named in the same sentence as RUNX1 in open-access papers (continued):
Sharing a sentence is not in itself a finding about the gene and the disease.
leukemia (continued). "A study involving leukaemia reported that Wnt/β-catenin signalling increases the expression of the ETO and RUNX1 genes in human haematopoietic progenitors, and the distal P1-RUNX1 promoter is a direct transcriptional target of Wnt/β-catenin signalling." (PMID 31370857, 2019). "ChREBP and its downstream molecules, including TXNIP, RUNX1 and GATA2, may be ideal therapeutic targets for certain types of leukemia." (PMID 27224916, 2016). "Presence of ETV6/RUNX1 alone is usually not sufficient for leukemia onset, and additional genetic alterations have to occur in ETV6/RUNX1-positive cells to cause transformation." (PMID 26919255, 2016). "The fact that the majority of the Mx1-Cre+; Cbfb+/56M; Runx1+/lz mice eventually develop leukemia does not necessarily mean that the fusion protein's RUNX1-independent activities are sufficient for leukemia development, if given enough time." (PMID 27542261, 2016). "A second possible explanation for the accelerated leukemia development by the CBFβ-SMMHC d179-221 mutant is that it alters the amount of RUNX1 available to non-fusion protein complexes." (PMID 27542261, 2016). "Furthermore, both RUNX1 and its leukemic fusion protein RUNX1/ETO influence expression of a number of microRNAs in normal differentiation and leukemia." (PMID 26990877, 2016). "A shorter variant of RUNX1/ETO, RUNX/ETO9a, lacking the C-terminal domain of ETO induces leukemia in murine bone-marrow transplantation models." (PMID 26990877, 2016). "Together, these findings indicate that high affinity binding of RUNX1 is not required for CBFβ-SMMHC induced leukemia." (PMID 27542261, 2016). "Interestingly, both CBF leukemia fusion proteins and miR-17, which targets RUNX1-3′UTR, negatively affect a common core RUNX1-miRNA mechanism that forces myeloid cells into an undifferentiated, KIT-induced, proliferating state." (PMID 25612891, 2015). "In support of this possibility, a dominant-negative RUNX1 translocation has been found in a subset of leukemias, and expression of this protein blocks the differentiation of leukemic cells and promotes the self-renewal of hematopoietic stem cells." (PMID 25894653, 2015). "Etv6 and Runx1 are known leukemic regulators, and Suz12 and Ezh2 are core members of the Polycomb repressive complex 2 (PRC2), whose activities have been shown to be essential for MLL-AF9 driven leukemia." (PMID 25517911, 2014). "In contrast, RUNX1/RUNX1T1- positive leukemic cells did not re-establish leukemia in secondary recipients." (PMID 25568664, 2014). "Furthermore, recent studies have shown that an alternatively spliced isoform of RUNX1/ETO lacking the C-terminal N-CoR binding domain coexists with full length RUNX1/ETO in patients and strongly induces leukemia development in mice." (PMID 23865046, 2013). "Deregulation of RUNX1-target miRNAs, however, is often observed also in non-CBF leukemia samples, indicating that these miRNAs can be targeted by other TFs, and/or that factors other than cytogenetic abnormalities can affect RUNX1 function or expression." (PMID 23344057, 2013). "Remarkably, KIT is often overexpressed in CBF leukemia concomitantly with miR-222-221 downregulation, suggesting that miR-222-221 may be under the transcriptional control of CBF (i.e., RUNX1 and CBFB)." (PMID 23344057, 2013). "Expression of RUNX1/ETO in primitive hematopoietic cells leads to increased cell survival, proliferation, and a delay in myelo-erythroid differentiation which certainly contributes to the onset of leukemia development." (PMID 23865046, 2013). "Interestingly, treatment with entinostat did not induce an increase in phospho-γH2A.X in healthy CD34+ cells (hCD34+), implying that disruption of the RUNX1/PTBP1 interaction induces double stranded breaks in leukemia cells, but not in healthy HSPCs." (PMID 41214140, 2026).
leukemia (continued). "Importantly, mice with conditional knockin of Cbfb-MYH11 over Runx1-null background did not develop leukemia, suggesting that Runx1 is indispensable for leukemogenesis by Cbfb-MYH11." (PMID 40763310, 2025). "Moreover, similar results were observed in cells cotransfected with mRUNX1b-R174Q and these fusion proteins, despite the absence of leukemia development in Runx1+/R188QMx1-CreCbfb+/56M mice." (PMID 40763310, 2025). "The presence of the compensation mechanism among RUNX family members (RUNX1, RUNX2, and RUNX3) prompted us to imagine that targeting whole RUNX family could be an effective strategy to suppress the malignant phenotypes of leukemia cells." (PMID 40171874, 2025). "GO analyses indicate that the JMJD1C and RUNX1 directly co-activated genes in MOLM-13 cells are involved in the cell cycle, DNA replication, and cell division processes, all of which are necessary to maintain the hyper-proliferation features and differentiation defects of leukemia cells." (PMID 39450904, 2025). "Despite of this, a recent report has provided important evidence challenging the idea that RUNX1 overexpression may not play a role in leukemia." (PMID 37670378, 2023). "In leukemia cell lines HL60 and Jurkat, and CD34+ progenitor cells, induction of the Wnt/β-catenin signal increases the expression of the RUNX1 P1 isoform, which may be critical for leukemia onset and progression; in colon cancer cells, RUNX2 was found to be upregulated by the same pathway." (PMID 36429115, 2022). "As these experiments require the exogenous expression of tagged proteins the levels of RUNX1 and the fusion do not precisely reflect the situation in pre-leukemia/leukemia but show that ETV6-RUNX1 can compete with RUNX1 and does so more effectively at sites with RUNX motifs." (PMID 36411286, 2022). "RUNX1 is a member of the RUNX family of transcription factors (RUNX1, RUNX2 and RUNX3), and is known to influence the malignancy of many neoplasms, including leukaemia, and to act as an oncogene or tumour suppressor gene with diverse functions depending on the tumour." (PMID 36085167, 2022). "Taking these differences into account, we still noted that several genes were missing in the PanelApp panels which most likely would fulfill their criteria, for instance the leukemia predisposing genes ETV6 and RUNX1 (not mentioned) and the hereditary paraganglioma gene SDHB (marked red)." (PMID 34061292, 2021). "Similarly, mice expressing RUNX1‐ETO under the control of the hMRP8 promoter failed to develop leukaemia as well." (PMID 34766123, 2020). "Interestingly, in both systems, no leukaemia developed, although mice expressed high levels of RUNX1‐ETO in the bone marrow and progenitors showed abnormal maturation and increased self‐renewal." (PMID 34766123, 2020). "The molecular mechanisms by which RUNX1/ETO promotes CCND2 expression highlights the complexity of how leukemogenic transcription factors reprogram the epigenome and establish an aberrant transcriptional network essential for leukemia maintenance and self-renewal." (PMID 30300583, 2018). "Therefore, our finding that hematopoietic transcription factors, such as TAL1 and RUNX1, influence expression of PRKACB isoforms could connect aberrant transcription factor function with altered PKA signalling in leukemia." (PMID 29069738, 2017). "Possible biological explanations for that involve the persistence of RUNX1/RUNX1T1 in pre-leukemic clones, as well as the development of an immunosurveillance effective in preventing disease reoccurrence by the autologous immune system or by Graft-vs-Leukemia effects after allo-HSCT." (PMID 28587190, 2017). "Consequently, AML1-ETO occupies and deregulates RUNX1 target genes, as well as localizes to subnuclear sites that are distinct from those where RUNX1 resides, thus resulting in leukemia phenotype." (PMID 28611288, 2017).
leukemia (continued). "Interestingly, there exist dose effects of both RUNX1 and GATA2 in leukemia development because either too low or too high levels of these proteins significantly influence the initiation, maintenance and relapse of leukemia." (PMID 27224916, 2016). "The ability of Myb to contribute to leukemogenesis is likely through its direct activation of a number of leukemia-promoting genes including Myc, CCNB1, Bcl2, Smyd2, and GFI1, as well as its direct repression of key differentiation regulators containing Sfpi1, Runx1, Junb, and Cebpb." (PMID 27863435, 2016). "The L-MC for RUNX1/RUNX1T1 could not be defined because the related leukemia was not retransplantable, indicating that RUNX1/RUNX1T1 does not completely transform HSPCs." (PMID 25568664, 2014). "However, in contrast to primary AML patient samples, RUNX1/ETO-selected progenitor cells fail to induce leukemia development in immunocompromised NOD/SCID mice, thereby suggesting that additional genetic events are necessary for leukemia development." (PMID 24348510, 2013). "Similarly to RUNX1, CBFB is also a target of chromosome rearrangements in leukemia." (PMID 23344057, 2013). "MiRNA-based deregulation of RUNX1 expression could explain why non-CBF leukemias are often characterized by molecular defects, such as KIT upregulation, typically produced by CBF karyotypic abnormalities." (PMID 23344057, 2013). "ETV6/RUNX1 (E/R) (also known as TEL/AML1) is the most frequent gene fusion in childhood acute lymphoblastic leukemia (ALL) and also most likely the crucial factor for disease initiation; its role in leukemia propagation and maintenance, however, remains largely elusive." (PMID 22028862, 2011). "ETV6::RUNX1, the most common oncogenic fusion in pediatric B cell precursor acute lymphoblastic leukemia (BCP‐ALL), induces a clinically silent preleukemic state that can persist in carriers for over a decade and may progress to overt leukemia upon acquisition of secondary lesions." (PMID 40177616, 2025). "Given that leukemia development requires the acquisition of multiple genetic aberrations, the study of primary cells from patient leukemic samples does not allow easy discrimination of the impact of RUNX1-ETO alone on the gene regulatory network of normal blood progenitor cells." (PMID 32460028, 2020). "In leukemia the single cell functional plasticity of the RUNX1-miR-221-KIT axis that regulates normal proliferation and differentiation can be undermined not only by the RM8 fusion protein, but also by genetic mutations, including other non-random cytogenetic rearrangements affecting RUNX1 or CBFB." (PMID 29156756, 2017). "However, Alox5 is not essential for the induction of leukemia by RUNX1-ETO9a in vivo." (PMID 24130502, 2013). "We then enriched leukemia stem cell activity of these RUNX1-ETO9a cells through tertiary and quaternary transplantation, finally resulting in the generation of aggressive AML cells capable of producing leukemia in 10 days even in non-irradiated recipient mice." (PMID 38702444, 2024). "As mentioned, RUNX1::RUNX1T1 alone was not able to induce leukemogenesis in mice, prompting the question of additional co-activators necessary to induce leukemia in mice." (PMID 38201282, 2023). "Further, mice genetically engineered to express AML1/ETO (RUNX1/RUNX1T1) have been shown to have a normal life span and do not develop leukemia at all." (PMID 35565315, 2022).
leukemia (continued). "Re-expression of WT but not KR mutant PKM2 inhibited the expression of RUNX1, but not the other core-binding factor family members RUNX2 or RUNX3 in NB4, U937 and 32DBCR-ABL leukemia cells, suggesting that SUMOylation of PKM2 is essential in modulating RUNX1." (PMID 33473116, 2021). "To determine whether disruption of the RUNX1/PTBP1 interaction differentially affected the LSC and non-LSC cells, we treated mouse CM+ leukemia cells with entinostat for 24 h, and examined glucose uptake in these populations." (PMID 41214140, 2026). "In contrast, transplantation of cells taken from RUNX1/ETO knockdown mice (RE-KD; LNP/siRE-mod primary treatment) resulted in significantly prolonged median survival of 210 days (p < 0.0016) with 50% of the transplanted mice not developing leukaemia at all." (PMID 36823395, 2023). "Because Ro5-3335 inhibits RUNX1 and not just the CBFβ-SMMHC fusion protein, it may also be useful for the treatment of other leukemia subtypes that require RUNX1 activity." (PMID 27542261, 2016). "Consistently, RUNX1, but not GATA2, was remarkably upregulated in ChREBP-null leukemia cells, which could be partially suppressed by the ectopic expression of TXNIP." (PMID 27224916, 2016). "However, despite robust expression of the RUNX1-ETO fusion transgenes in the BM upon tetracycline withdrawal in the first model and efficient excision of the floxed STOP codon in the second model, no leukaemia developed." (PMID 30669675, 2019).
acute myeloid leukemia (453 papers, 1999 to 2026). Acute myeloid leukemia (AML) is a group of neoplasms arising from precursor cells committed to the myeloid cell-line differentiation. "The runt-related transcription factor 1 (RUNX1) gene encodes a transcriptional factor that is crucial in hematopoiesis and is mutated in ∼10% of adult acute myeloid leukemia (AML) cases." (PMID 40427601, 2025). "Their study included 54 patients with a type of δ-SPD (17 δ-SPD patients, 22 HPS, 13 familial platelet disorders and predisposition to acute myelogenous leukemia [RUNX1], and 2 combined αδ-granule deficiency)." (PMID 41362696, 2025). "RUNX1 is an oncogenic transcription factor and a recognized driver mutation in acute myeloid leukemia (AML), where it plays a key role in regulating CCND2 expression." (PMID 40508126, 2025). "In the 2016 World Health Organization (WHO) classification, germline monoallelic alterations in RUNX1 had been incorporated as a new subgroup: Familial Platelet Disorder with a predisposition to Acute Myeloid Leukemia (FPD/AML)." (PMID 40427601, 2025). "Up to 30% of RUNX1 disease-causing genetic variants in adult patients with acute myeloblastic leukemia have been reported to be germline." (PMID 40563486, 2025). "For example, the RUNX1 gene had the highest association score of 0.8 with acute myeloid leukemia, and a score of only 0.1 with DS." (PMID 39290359, 2024). "A study of radiation-related myelodysplastic syndrome (MDS) and acute myeloid leukemia (AML) patients among Hiroshima atomic bomb survivors showed that 46% of the patients who succumbed to the disease carried point mutations in the RUNX1 gene." (PMID 36672189, 2023). "Germline monoallelic RUNX1 mutations, on the other hand, strongly predispose families to familial platelet disorder with associated acute myeloid leukemia (FPD/AML)." (PMID 37190015, 2023). "Approximately 20% to 25% of adults with acute myeloid leukemia have mutations involving the myeloid transcription factors Runt-related transcription factor 1 (RUNX1), CEBPA, and/or GATA binding protein 2 (GATA2)." (PMID 37047003, 2023). "In acute myeloid leukaemia (AML) RUNX1 mutation is characterised by certain clinicopathological features with poor prognosis and adverse risk by the European LeukemiaNet recommendation." (PMID 37188777, 2023). "Approximately 44% of patients with familial platelet disorders that are predisposed to hematologic malignancies caused by autosomal dominant RUNX1 mutations progressed to acute myeloid leukemia caused by second-hit mutations in CDC25C or other genes." (PMID 36515795, 2023). "Other mutations in RUNX1 are also associated with acute myeloid leukemia, T-cell acute lymphoblastic leukemia (present in ∼15% of cases), pancreatic cancer, myelodysplastic disorders, and a variety of other tumors." (PMID 38028440, 2023). "RUNX1 mutations were previously shown to be associated with acute myeloid leukemia occurrence and were also found in ALL." (PMID 36005134, 2022). "A germline RUNX1 mutation is associated with predisposition to mainly acute myeloid leukemia (AML) and myelodysplastic syndromes (MDS) while some cases with various lymphoid malignancies have also been reported." (PMID 36185231, 2022). "Acute myeloid leukemia (AML) with mutated RUNX1 (RUNX1mut) has an adverse prognosis based on the 2022 European LeukemiaNet risk stratification." (PMID 36358658, 2022). "For instance, somatic mutations in RUNX1 are highly associated with acute myeloid leukemia (AML) progression with the majority having oncogenic functions." (PMID 36231078, 2022). "C/EBPα, PU.1, and RUNX1 are frequently mutated in acute myeloid leukemia (AML), which can arise from reduced transcription activity and impede myeloid differentiation." (PMID 33770473, 2021). "In humans, the RUNX1 gene is frequently targeted by translocation or mutation in acute myeloid leukaemia (AML) and other myeloproliferative disorders." (PMID 34440349, 2021).